VIM (vimentin)
Diseases named in the same sentence as VIM in open-access papers (continued):
Sharing a sentence is not in itself a finding about the gene and the disease.
glioma (continued). "High vimentin expression was an independent significant prognostic factor for poor survival in high-grade glioma patients while low vimentin expression a biological indicator of better response to temozolomide therapy for glioblastoma patients." (PMID 31968004, 2020). "Of the genes identified in the bulk RNA-seq analysis, only FN1, CDH2, and CDH11 were expressed in the glioma single-cell RNA-seq data, so we also visualized VIM as a post-EMT marker and SFRP1 as a pre-EMT marker." (PMID 33319914, 2020). "miR-21 overexpression promoted the capacity of glioma cells to migrate and invade and increased the epithelial marker E-cadherin protein, while decreasing the mesenchymal markers VIM, Snai2, and TWIST." (PMID 33085646, 2020). "MiR-1298-3p agonist downregulated the NID1 and vimentin levels, but upregulated the level of E-cadherin in glioma cells." (PMID 32355035, 2020). "In the present study, we showed the EMT suppressive mechanism of FOXD2-AS1 knockdown in glioma cells by upregulating E-cad and suppressing N-cad and vimentin expression." (PMID 33336050, 2020). "In glioma, vimentin expression appears to be related to cell density and chemoradiotherapy; it is detected mainly in low-density cell cultures." (PMID 32670437, 2020). "Our findings are in agreement with published report whereby loss of NF1 by shRNA promoted glioma cell invasion and upregulation of EMT markers such as vimentin, SNAI, TWIST1, ZEB1, and ZEB2." (PMID 30967630, 2019). "This includes the effect of the observed overexpressions, like spastin, vimentin, nestin, actin cross-linkers, etc., on migration and the underlying mechanisms, but also how migration associated signaling is altered in glioma and whether this can be used for specifically targeting glioma migration." (PMID 31003495, 2019). "For detecting the effect of LINC00599 expression on EMT process, the change of epithelial marker (E-cadherin) and mesenchymal marker (vimentin) was measured in glioma cells by Western blot." (PMID 30867254, 2019). "We found that different isoforms of two proteins including vimentin and transgelin were differentially expressed in both tMSCs isolated from different gliomas." (PMID 28670517, 2017). "In glioma cells, hypoxic stress induced the expression of the mesenchymal markers Vimentin, N-Cadherin, and Snail1." (PMID 29212174, 2017). "Western blot results further confirmed that QUE significantly up-regulated MBP expression, but down-regulated vimentin (a marker for glioma) and GFAP expression." (PMID 28415586, 2017). "We also performed immunofluorescence analysis of H3K27me3, N-cadherin, and Vimentin in glioma cells." (PMID 29228694, 2017). "Three genes (TRIM28, DPYSL2 and VIM) were able to successfully distinguish gliomas from reference samples." (PMID 28498803, 2017). "In tMSCs isolated from low and high grade gliomas, different isoforms of mesenchymal-related proteins vimentin and transgelin were differentially expressed." (PMID 28670517, 2017). "It was observed that PTEN overexpression led to increased E-cadherin expression but decreased Vimentin expression at mRNA and protein levels in glioma cells." (PMID 28107197, 2017). "We first stained the intermediate filament Vimentin, a known marker of neural stem cells and early glial progenitors, also detected in gliomas and reactive astrocytes, but barely expressed in the normal brain." (PMID 28881750, 2017). "It has previously been suggested that vimentin, N-cadherin and the invasive marker E-cadherin are present at markedly elevated levels in numerous glioma cell lines and surgically resected specimens." (PMID 25777142, 2015).
glioma (continued). "Invasive potential of glioma cells in vivo was assessed by counting vimentin-positive cells crossing the solid tumor rim by immunohistochemical staining." (PMID 24884636, 2014). "A recent report identified a direct correlation between glioma grade and vimentin expression as well as a direct correlation between increased vimentin expression and temozolomide resistance." (PMID 25162558, 2014). "Our data indicated that knockdown of ENO1 resulted in restoration of E-cadherin expression and suppression of Vimentin expression in glioma cells." (PMID 24650096, 2014). "Regarding that EMT is closely associated with migration and invasion of cancer cells, we subsequently investigated the effect of OA on EMT processes of glioma cells by examining the changes in E-cadherin, N-cadherin, Vimentin and Twist1 expression." (PMID 23991044, 2013). "In contrast, we observed that IR induced the expression of N-cadherin, Vimentin and β-catenin proteins in glioma CSC." (PMID 23183822, 2012). "Here we elucidate, in part, the PKCε/vimentin‐dependent pathway that defines galectin‐1‐mediated glioma cell migration via integrin‐β1." (PMID 18947333, 2010). "In this study we describe the galectin‐1 regulation of integrin‐β1, PKCε and vimentin localization in human glioma cells." (PMID 18947333, 2010). "Alternately, the generation of MMP-9 and vimentin was increased by Snail in the glioma cell lines." (PMID 40575155, 2025). "Similarly, vimentin expression can be variable within gliomas, particularly in those undergoing histological transformation to higher-grade tumors." (PMID 40937216, 2025). "For example, tumors with high vimentin expression may be more responsive to therapies targeting tumor invasion and migration, while synaptophysin-positive gliomas could benefit from differentiation-inducing therapies." (PMID 40937216, 2025). "Vimentin also plays a role in distinguishing low-grade gliomas from glioblastomas." (PMID 40937216, 2025). "Olig2, GFAP, and vimentin are frequently used for glioma subtyping." (PMID 40362055, 2025). "Additionally, glioma stem-like cells (GSCs), which contribute to tumor recurrence and therapy resistance, have been shown to express high levels of vimentin, further implicating its role in glioma pathogenesis." (PMID 40937216, 2025). "The integration of immunohistochemical (IHC) and molecular markers, such as vimentin, synaptophysin, and H3K27me, has significantly enhanced the ability to distinguish between different glioma subtypes, particularly oligodendrogliomas and diffuse midline gliomas (DMGs)." (PMID 40937216, 2025). "In addition, it has also been reported that targeted inhibition of ZEB2 induced upregulation of E-cadherin expression and downregulation of vimentin expression leading to reduced invasion and migration of pediatric glioma and adult glioma cells." (PMID 39941886, 2025). "The role of vimentin in guiding therapy selection remains largely unexplored, and more research is needed to determine whether synaptophysin-positive gliomas have unique therapeutic vulnerabilities." (PMID 40937216, 2025). "For example, our detection of an increased number of previously undetected double-labeled GFAP- and vimentin-positive cells in low-grade glioma tissue may represent a malignant cell subpopulation in these tumors, usually not detected histologically." (PMID 38295184, 2024). "First, we analysed the expression of vimentin mRNA (VIM) in different glioma tumours." (PMID 36765531, 2023). "The analysis of RNA-seq data from TCGA databases showed significant upregulation of genes encoding mesenchymal markers and EMT regulators such as CDH2 (coding N-cadherin), VIM (coding Vimentin), SNAIs and TWISTs in tumor samples, particularly in high-grade human gliomas (grade 4) and MES-GBMs." (PMID 36900355, 2023). "Moreover, in high-grade glioma consecutive sections, the area with GAMs nearby expressed significantly less E-cadherin and more N-cadherin and Vimentin and vice versa." (PMID 36969175, 2023).
glioma (continued). "Likewise, the negative regulation of TMEM158 in glioma cells significantly increased the expression of E-Cadherin and decreased the expression of N-Cadherin, vimentin, and Snail." (PMID 37936608, 2023). "In addition, TMEM158 was overexpressed in U87MG, U251MG, and TJ905 glioma cells, E-Cadherin was downregulated while N-Cadherin, vimentin, and Snail was detected." (PMID 37936608, 2023). "The expression of vimentin in glioma tissues and cells was determined by RT-qPCR." (PMID 36765531, 2023). "Similarly, the expression of vimentin and N-cadherin were remarkably reduced in glioma cells transfected with miR-182-5p inhibitors, while the levels of E-cadherin were elevated." (PMID 38021156, 2023). "Importantly, a report on the upstream signaling pathway of the NLRP3 inflammasome in gliomas has been published, and activation of the ERK-dependent NF-κB has been shown to activate the NLRP3 inflammasome mediated by vimentin in EV-71-infected glioma." (PMID 37723542, 2023). "Additionally, we found that L1 overexpression resulted in upregulation of several VM formation‐related factors, including CD31, CD34, VEGFA, vimentin, and N‐cadherin, whereas it downregulated E‐cadherin expression in glioma cells." (PMID 36708044, 2023). "Glioma patients with high expression of Vimentin and Snail have a worse prognosis." (PMID 35928926, 2022). "Additionally, western blotting suggested that DLGAP1-AS1 knockdown increased E-cadherin expression and decreased vimentin expression in glioma cells." (PMID 35113786, 2022). "Similarly, the downregulation of N-cadherin and vimentin protein levels was statistically significant compared to controls in U87 glioma cells (p < 0.05)." (PMID 35571491, 2022). "The expression of E-cadherin in the siRNA1 and siRNA2 groups was significantly upregulated compared to control cells (siNC group), while protein levels of N-cadherin were significantly downregulated in U87 glioma cells, as well as the protein levels of vimentin." (PMID 35571491, 2022). "P2X7 inhibition may have affected glioma tumor cells spreading as evidenced by a decrease of matrix metalloproteinase-2 activity and decrease (β-catenin) or total reduction (N-cadherin and vimentin) of EMT-related proteins." (PMID 34964926, 2022). "It was revealed that, SNHG18 expression in glioma was up-regulated and associated with unfavorable prognosis of the patients; knockdown of SNHG18 repressed the malignant biological behaviors of glioma cells, enhanced E-cadherin expression and repressed N-cadherin and Vimentin expressions." (PMID 34937497, 2022). "Furthermore, the Transwell assay was employed to investigate the TCF12 regulation on E-cadherin, Vimentin and N-cadherin in glioma cells." (PMID 33413401, 2021). "To determine whether the exosome release blockade by R491 is the direct result of its vimentin targeting, we sought to knock out vimentin gene from human glioma U87 cells using the CRISPR-cas9 system." (PMID 34305581, 2021). "In glial cells, the interaction between plectin and IFs was first observed in rat glioma C6 cells, where the distribution of plectin was detected along vimentin filaments, and extensive crosslinking between plectin and reconstituted vimentin filaments was corroborated in vitro." (PMID 34572001, 2021). "Furthermore, we confirmed the strong expression of CD44, OPN and VIMENTIN in this glioma by immunohistochemical analysis." (PMID 34805184, 2021). "In our previous work, we demonstrated that overexpressed HMGA1 promoted proliferation, invasion, and migration in glioma cells, and Vimentin could directly bind to HMGA1." (PMID 34887392, 2021). "In addition, LASP1 was found to facilitate EMT in glioma and colorectal cancer cells, and interact with vimentin in HCC." (PMID 33722250, 2021). "TUBB3 and VIM have been identified in some human glioma cell lines before." (PMID 33251771, 2021).
glioma (continued). "Luo and coworkers have recently shown that STC1 levels directly correlate with those of matrix metalloproteinases (MMP)-2, MMP9, and vimentin in gliomas, and these authors hypothesized that STC1 augments the invasive capacities of glioma cells." (PMID 34394104, 2021). "Moreover, LBX2-AS1 depletoin not only downregulated LIF and p-STAT3 in glioma cells, but also affected the protein levels of N-cadherin, E-cadherin and Vimentin." (PMID 34729101, 2021). "Although we have previously identified an oncogenic ZEB2/miR-637/HMGA1 signaling axis targeting Vimentin which could promote both migration and invasion in glioma, little is known about the role of HMGA1 which is worthy of continuous investigation." (PMID 34887392, 2021). "NC reduced the expression of epithelial marker E‐cadherin in glioma cells, possibly by regulating the expression levels of transcription factors, and also increased the expression of mesenchymal markers N‐cadherin, vimentin, and β‐catenin, thereby inhibiting the EMT behavior of these cells." (PMID 33788424, 2021). "We measured the expression levels of E-cadherin and Vimentin proteins to assess whether the phenotype of glioma cells in the U87-C population were transformed into the mesenchymal phenotype." (PMID 32932941, 2020). "Besides, FOXO1 knockdown elevated protein levels of P‐PI3K, P‐AKT, CDK4, CCND1, c‐JUN, N‐cadherin and vimentin in glioma cells." (PMID 32902145, 2020). "Additionally, a study found that low vimentin was a favorable prognostic biomarker with a better response to temozolomide therapy, and vimentin expression was also related to grade of glioma patients." (PMID 32257943, 2020). "Although vimentin is the major cytoskeletal component present in immature glia, it is expressed to the same extent in all grades of astrocytic tumors and correlated with the malignancy grade in gliomas." (PMID 32998285, 2020). "Vimentin was postulated as a molecular marker presenting enhanced motility and invasion in gliomas." (PMID 31968004, 2020). "Current investigations by our group address the question of whether similar mechanisms to the ones found in macrophages, endothelial cells, glioma, or astrocytes that release vimentin by exosomal secretion also exist in neurons." (PMID 33240046, 2020). "While the amount of vimentin and the glioma stem cell marker nestin showed a negative correlation with patient prognosis and/or glioma staging, an association of GFAP expression with staging is controversial." (PMID 31003495, 2019). "Expression of E-cadherin, N-cadherin and Vimentin in glioma cells were explored." (PMID 31770107, 2019). "Our study also demonstrated that down-regulated FOXD2-AS1 repressed proliferation, colony formation, migration, invasion and EMT (significantly increased E-cadherin expression, clearly declined N-cadherin and Vimentin expression) while stimulating apoptosis of glioma cells." (PMID 31770107, 2019). "Glioma cells may express the intermediate filaments vimentin, GFAP, nestin, synemin, and α-internexin." (PMID 31003495, 2019). "In addition, CBX7 was found to regulate negatively migration and invasion via upregulation of E-cadherin and downregulation of matrix metalloproteinase (MMP)-2, MMP-9, and vimentin in glioma." (PMID 31709304, 2019). "Furthermore, a potent chemotherapy drug doxorubicin has been identified to induce epithelial-mesenchymal transition (EMT) in glioma cells via elevated expression of vimentin and reduced expression of E-cadherin in U87MG glioma cells." (PMID 31052435, 2019). "However, the effect of vimentin on the Nogo-66 receptor, which contributes to the myelinated invasiveness of glioma, remains elusive." (PMID 31649250, 2019). "In astrocytes it could furthermore be demonstrated that vimentin was necessary to maintain their polarization, indicating a possible important role for vimentin in explaining the effects of IDH1 mutations on glioma behavior." (PMID 31242696, 2019).
glioma (continued). "Univariate and multivariate analysis of biomarker expression in the treatment-naïve glioma cohort showed significantly lower values for vimentin (p = 0.0002), VEGFR2 (p = 0.0002), nestin (p = 0.003), Ki67 (p = 0.006) and HLA1 (p = 0.008) proteins in IDHmt vs wt tumors." (PMID 31881020, 2019). "Our findings expand upon the current understanding of the migration/invasion of GBM and imply that the maturation process of NgR via vimentin may be a therapeutic target for glioma." (PMID 31649250, 2019). "Since the promoting effect of TAZ on glioma cell migration and invasion was observed by transwell and scratch assay, we detected the expression of mesenchymal markers, Vimentin and N-cadherin, the result showed that they both were downregulated when TAZ was inhibited." (PMID 27764783, 2016). "Interestingly, glioma cells also exhibited lower transcript levels of N-cadherin, Vimentin and Fibronectin, and upregulated E-cadherin transcript after incubation with 100 μM TMZ for 48 h." (PMID 27894350, 2016). "Interestingly, a recent study showed that an RNA aptamer (APT) which binds secreted OPN in the extracellular space significantly decreased vimentin expression and knockdown of OPN resulted in decreased vimentin expression in in glioma cells." (PMID 26824421, 2016). "Therefore, the present study examined the expression levels of vimentin, N-cadherin and E-cadherin in glioma cells by western blotting." (PMID 25777142, 2015). "In addition, a recent report identified a positive correlation between glioma grade and vimentin expression and these same authors found that temozolomide resistance is associated with an up-regulation of vimentin." (PMID 25162558, 2014). "Dbait32Hc-induced vimentin Ser459 phosphorylation was found in various human cell lines, including MRC-5 (transformed fibroblasts), SK28 (skin melanoma), AT5BI (ATM-deficient fibroblasts) and M059K (glioma) cells." (PMID 24282534, 2013). "Galectin‐1 has been implicated in glioma adhesion and migration 5, 6, 7, 32, and in this report we suggest that the galectin‐1 influence on integrin‐β1, PKCε, and vimentin localization provides evidence that galectin‐1 utilizes integrin trafficking pathways to impel glioma malignancy." (PMID 18947333, 2010). "Interestingly, the vimentin that has been identified in some human glioma cell lines was not detectable in NG97 cells." (PMID 15885136, 2005). "Furthermore, investigations into the regulatory mechanisms governed by Snail have unveiled its ability to modulate the expression of critical EMT-associated molecules such as E-cadherin, Notch1, vimentin, and MMP-9 in various cancer cell types, including gliomas." (PMID 40575155, 2025). "Amongst GFAP-expressing cells, we observed a ~30% increase in the fraction that were vimentin-positive (p = 0.036, 2-tailed paired t-test, n = 3 tissue samples from different patients), suggesting that even in low-grade gliomas, a vast majority of tumor cells may be aggressive." (PMID 38295184, 2024). "Our results showed that the facilitation of IRAK1 on glioma cell migration and invasion could be partially explained by the upregulated expression of E-cadherin and the downregulated expression of N-cadherin and Vimentin." (PMID 37031183, 2023). "We found that Chalcone 9X treatment inhibited cell migration and protein expressions of N-cadherin and Vimentin were repressed, while E-cadherin was increased, which confirmed that Chalcone 9X could repress migration in glioma cells, but the potential mechanisms remained unclear." (PMID 35978634, 2022). "Furthermore, the expression of mesenchymal markers including N-cadherin, Fibronectin1, Vimentin increased upon NE intervention, suggesting that NE could enforce the mesenchymal-like phenotype of glioma cells." (PMID 35219305, 2022).